LCE2C (late cornified envelope 2C)
Description:
Precursors of the cornified envelope of the stratum.
Synonyms: LEP11
Tractability: No criterion of Open Targets' tractability assessment is met for any kind of drug.
Gene: Protein-coding gene on chromosome 1 (152,675,279 to 152,676,569, forward strand). Ensembl gene ENSG00000187180.
Pathways (Reactome):
Developmental Biology: Formation of the cornified envelope
Gene Ontology:
Molecular function: identical protein binding; protein binding
Biological process: epidermis development
Genetic constraint (gnomAD): Loss-of-function variants: 0 observed, 0.46 expected, observed/expected ratio (o/e) 0, 90% interval 0 to 1.84. That is too few expected variants to judge how well the gene tolerates losing a copy. Missense variants: 179 observed, 142.89 expected, observed/expected ratio (o/e) 1.25, 90% interval 1.11 to 1.42. Synonymous variants: 57 observed, 49.38 expected, observed/expected ratio (o/e) 1.15, 90% interval 0.93 to 1.44.
Homologues: Paralogues in human: LCE2D (96% identical), LCE2B (95% identical), LCE2A (87% identical), LCE1E (75% identical), LCE1F (75% identical), LCE5A (74% identical), LCE1D (73% identical), LCE3D (55% identical), LCE3E (54% identical), LCE3B (51% identical), LCE3C (50% identical), LCE3A (49% identical), and 8 more.
Diseases named in the same sentence as LCE2C in open-access papers:
LCE2C is named in the same sentence as 2 diseases in open-access papers, as found by Europe PMC text mining. Sharing a sentence is not in itself a finding about the gene and the disease. The quoted sentences say what the papers report.
keratoconus (1 paper, 2023). A degenerative, structural disorder of the eye, characterized by a cone-shaped protrusion of the cornea. "We overlaid these 4 modules with FRGs and found that 8 FRGs (LCE2C, NOS2, AKR1C3, CAV1, MMD, LINC00618, SNCA, SLC7A11) were closely related to the disease state of keratoconus." (PMID 37626095, 2023).
LCE2C also shares sentences with these, for which no sentence is quoted: lung carcinoma (1 paper).